GMPR2 (guanosine monophosphate reductase 2)
Description:
Catalyzes the irreversible NADPH-dependent deamination of GMP to IMP. It functions in the conversion of nucleobase, nucleoside and nucleotide derivatives of G to A nucleotides, and in maintaining the intracellular balance of A and G nucleotides. Plays a role in modulating cellular differentiation.
Synonyms: GMPR 2; hGMPR-II
Tractability: Small molecule: a structure with a bound ligand is known; it has a high-quality binding pocket. PROTAC: ubiquitination databases record sites on it; its protein half-life has been measured.
Target class: Enzyme; Oxidoreductase
Gene: Protein-coding gene on chromosome 14 (24,232,211 to 24,239,246, forward strand). Ensembl gene ENSG00000100938.
Subcellular location (Human Protein Atlas): Nucleoplasm; Nucleoli
Pathways (Reactome):
Metabolism: Purine salvage
Gene Ontology:
Molecular function: GMP reductase activity; protein binding; catalytic activity; oxidoreductase activity
Biological process: GMP metabolic process; nucleotide metabolic process; purine nucleotide metabolic process
Cellular component: cytosol; GMP reductase complex
Genetic constraint (gnomAD): Loss-of-function variants: 26 observed, 28.35 expected, observed/expected ratio (o/e) 0.92, 90% interval 0.67 to 1.27. The upper end of that interval is the gene's LOEUF score, 1.27, which puts it in group 5 of 6, group 1 being the genes least tolerant of losing a copy. Missense variants: 296 observed, 336.17 expected, observed/expected ratio (o/e) 0.88, 90% interval 0.8 to 0.97. Synonymous variants: 120 observed, 120.07 expected, observed/expected ratio (o/e) 1, 90% interval 0.86 to 1.16.
Homologues: Orthologues: chimpanzee GMPR2 (99% identical), macaque GMPR2 (99% identical), dog GMPR2 (97% identical), guinea pig GMPR2 (96% identical), rat Gmpr2 (96% identical), mouse Gmpr2 (95% identical), pig GMPR2 (89% identical), rabbit GMPR2 (88% identical), tropical clawed frog gmpr2 (84% identical), zebrafish gmpr2 (80% identical), Caenorhabditis elegans T22D1.3 (26% identical). Paralogues in human: GMPR (79% identical), IMPDH1 (31% identical), IMPDH2 (30% identical).
Diseases named in the same sentence as GMPR2 in open-access papers:
GMPR2 is named in the same sentence as 15 diseases in open-access papers, as found by Europe PMC text mining. Sharing a sentence is not in itself a finding about the gene and the disease. The quoted sentences say what the papers report.
cancer (2 papers, 2021 to 2024). A tumor composed of atypical neoplastic, often pleomorphic cells that invade other tissues. "In addition, the role of genes closely related to HPRT1, such as GMPR2 and phosphoribosyl transferase domain containing (PRTFDC1), in pan-cancer needs to be addressed." (PMID 38159260, 2024).
GMPR2 also shares sentences with these, for which no sentence is quoted: adult-onset Still disease (1 paper); autism (1); COVID-19 (1); epilepsy (1); Hypertension (1); infection (1); keratosis (1); mental disorder (1); metabolic disorder (1); personality disorder (1); pulmonary disorder (1); retinitis pigmentosa (1); schizophrenia (1); tumor (1).